HOXA9 (homeobox A9)
Diseases named in the same sentence as HOXA9 in open-access papers (continued):
Sharing a sentence is not in itself a finding about the gene and the disease.
tumor (continued). "In addition, the inhibitors of HOXA9 play a crucial role in tumor therapy through indirectly regulation of HOXA9 expression, no directly small molecular inhibitors targeting HOXA9 are developed at present." (PMID 36376832, 2022). "However, HoxA9 expression is too low to be detected both in liver normal and tumor tissues (data not shown) in our experiment." (PMID 34344448, 2021). "Thus, Zeb1 acts as a tumor suppressor in MLL-AF9 and Meis1a/Hoxa9 AML LSCs." (PMID 33108352, 2021). "This could be because the marker was truly non-existent in some patients; however, meth-HOXA9 was detected in all tumor samples which makes this unlikely." (PMID 33322500, 2020). "The tissue fibrosis, in turn, raises the stiffness of the surrounding microenvironment of the tumor compared to the surrounding tissue, thereby accelerating the progression of the cancer by lowering the concentrations of the tumor suppressors PTEN and HOXA9 within the cancer cells." (PMID 33043017, 2020). "Thus, sustained expression of HOXA9 and HOXC8 may provide a potential therapeutic strategy to inhibit tumor growth in glycolysis-exuberant cancer." (PMID 31013831, 2019). "HOXA9 had little effect on levels of other classical cadherins, but it is not possible to exclude the possibility that HOXA9 might also promote tumor cell aggregation by inducing expression of other types of adhesion molecules." (PMID 25023983, 2014). "While this work was in preparation, three new miR-210 targets were validated, i.e. HOXA1, HOXA9 and FGFRL1, and the analysis of tumour xenografts derived from cancer cell lines overexpressing miR-210 suggested a potential involvement of miR-210 in tumour growth initiation." (PMID 20436681, 2010). "Our studies concluded that miR-182 is a tumor-suppressor gene and inhibits the self-renewal of LSC but not HSPC via targeting BCL2 and HOXA9, suggesting that miR-182 is potential therapy target for LSC." (PMID 36593968, 2023). "For both HOXA9 and ISL1, there was a significant increase in the mean level of methylation in the recurrence and progression tumours compared to their no-recurrence counterparts." (PMID 26332997, 2015). "Our study revealed that the upregulation of HOXA9 in KIRP could mainly be due to CNVs because no differential methylation was detected between normal and primary tumor samples." (PMID 38904676, 2024). "Since Prep1 exerts a tumor suppressive function, we tested whether the absence of Prep1 would allow Meis1 to induce AML in vivo without HoxA9 overexpression." (PMID 24809472, 2014).
cancer (118 papers, 2007 to 2026). A tumor composed of atypical neoplastic, often pleomorphic cells that invade other tissues. "While both PAX1 and HOXA9 (or related HOX genes) have been studied in the context of cancer-related methylation, their presence in the same diagnostic panels does not imply direct functional cooperation between them." (PMID 40699796, 2025). "On the other hand, HOXA9 has been implicated in regulating Notch signaling, particularly in hematologic malignancies and some solid tumors." (PMID 40699796, 2025). "Among the 11 TCGA cancer types, HOXA9 exhibited the highest mutation frequency, with 9% in STAD, 2% in LUSC, and 1% in the remaining tumors." (PMID 38904676, 2024). "Subsequently, we determined the expression of HOXA9 in diverse cell lines associated with each cancer type retrieved from the CCLE portal." (PMID 38904676, 2024). "As published previously, HOXA9 plays a profound role in regulating cancer-associated biological events when aberrantly expressed in cancer." (PMID 38904676, 2024). "For cancer related genes, Nav3, Cenpf, Muc5Ac, Mpp7, Gas1, MageD2, Dusp1, Ros, Polr2a, Rragd, Ros1, and Hoxa9 are mutated." (PMID 32793490, 2020). "As a proto-oncogene, high expression levels of HOXA9 are often associated with increased cancer risk." (PMID 31013831, 2019). "Our data implicated HOXA9 in several hallmarks of cancer, including cell proliferation, invasion, DNA repair pathways, and cancer stem cell features." (PMID 25762636, 2015). "Together, these analyses suggest that the HOXA9-transcriptome is enriched for genes involved in stem-like cell features, a critical hallmark of cancer." (PMID 25762636, 2015). "Similarly, Hoxa9, a homeobox gene associated with poor prognosis in various cancers, has been implicated in promoting tumorigenesis through stemness and differentiation pathways." (PMID 41282050, 2025). "Hence, the dysregulation of HOXA9 expression underscores its potential as a key player in the molecular mechanisms associated with cancer progression." (PMID 38904676, 2024). "Through extensive computational analysis using experimentally validated datasets, we concluded that HOXA9 could serve as a potential diagnostic biomarker for cancer detection and stage stratification." (PMID 38904676, 2024). "Then, we investigated the potential association between the upregulation of HOXA9 expression and epigenetic variation by examining the promoter DNA methylation status across all 11 TCGA cancer types using the same GDC-TCGA datasets employed for gene expression analysis." (PMID 38904676, 2024). "The overexpressed HOXA9 activates TGFβ2 and promotes the transformation of normal peritoneal fibroblasts and normal adipose and bone marrow–derived mesenchymal stem cells (MSCs) into cancer-associated fibroblasts (CAFs)." (PMID 34617205, 2022). "Further mutations in cancer-related genes included Nav3 (V1129L), Cenpf (D1327E), Muc5ac (A429P), Mpp7 (Q158R), Gas1 (G326R), Maged2 (A473S), Dusp1 (C24R), Ros1 (W1875C), Polr2a (M1102I), Rragd (L385P), and Hoxa9 (insertion of “G” in UTR)." (PMID 32793490, 2020). "Dysregulated activation of the HOXA9 is a hallmark of a variety of carcinomas." (PMID 32243061, 2020). "This study indicates a novel mechanism by which a cancer risk variant contributes to the HOXA9 overexpression, which may lead to epigenome reprogramming and protein–protein interaction to promote leukemogenesis." (PMID 31013831, 2019). "In addition to investigating the clinical significance of HOXA9 in prognosis and cancer stages, we identified a potential association between HOXA9 expression and various immune subtypes across cancers, enabling us to correlate HOXA9 expression with individual immune cell types." (PMID 38904676, 2024). "Transcriptomic analysis of HOXA9-depleted cells revealed the downregulation of multiple pathways, with the most significant being "pathways in cancer"." (PMID 41904140, 2026).
cancer (continued). "Our findings with the OncoMe panel (SHOX2, RASSF1A, SEPTIN9, and HOXA9) in malignant ascites are consistent with and extend previous reports on DNA methylation biomarkers in body fluids." (PMID 41477641, 2025). "By using the optimal methylation cutoff value for individual genes, the positive detection rates of each marker in malignant tumor patients ranked from high to low were 46.3% (HOXA9), 45.1% (SHOX2), 31.1% (SEPTIN9) and 18.9% (RASSF1A)." (PMID 41477641, 2025). "As a transcription factor, HOXA9 exerts its influence by regulating a diverse set of targets that contribute to cancer-related events, further emphasizing its significance in the context of oncology." (PMID 38904676, 2024). "Through our extensive computational analysis, we deduced that HOXA9 serves as a potential biomarker across various cancers, laying the groundwork for further investigation into its role in specific cancer types." (PMID 38904676, 2024). "Our analysis of drug‒gene interactions revealed that drugs such as linifanib, sorafenib, sunitinib, and midostaurin have the potential to target HOXA9 in cancer, thereby increasing chemosensitivity in cancer cells." (PMID 38904676, 2024). "Despite numerous reports on its aberrant expression in a few malignancies, the molecular and functional complexity of HOXA9 across cancers remains obscure." (PMID 38904676, 2024). "HOXA9 is upregulated in the majority of malignancies and drives cancer progression by regulating multiple signaling mechanisms." (PMID 38904676, 2024). "There is a need to validate these findings through experimental work, both in vitro and in vivo, to elucidate the HOXA9-mediated dynamics of cancer progression." (PMID 38904676, 2024). "In the present study, we identified 12 miRNAs, including two HOX cluster-embedded miRNAs, namely hsa-miR-196a-5p and hsa-miR-196b-5p, that correlate the expression of HOXA9 across cancers." (PMID 38904676, 2024). "Understanding the correlation between HOXA9 expression and various immune cells has paved the way for clinicians to consider immunotherapy in various cancer types." (PMID 38904676, 2024). "We aimed to analyze the dynamic role of HOXA9 across cancers by identifying, analyzing, and understanding its multiple modes of regulation and functional implications and identifying possible therapeutic avenues." (PMID 38904676, 2024). "According to previous reports, in a few cancer types, HOXA9 is known to induce resistance to therapeutically approved drugs, namely erlotinib, bevacizumab, and temozolomide." (PMID 38904676, 2024). "In the present study, we systematically analyzed the expression status of HOXA9 in 33 different cancer types using datasets from GDC-TCGA." (PMID 38904676, 2024). "HOXA9 mRNA was highly elevated in the tissues of 9 solid cancers and downregulated in 2 of the cancer types compared to normal tissues." (PMID 38904676, 2024). "Initially, we checked the expression status of HOXA9 in TCGA cancer types using the TIMER 2.0 database." (PMID 38904676, 2024). "Elevated levels of HOXA9 were significantly correlated with immune cell infiltration in most cancer subtypes, particularly in KIRP." (PMID 38904676, 2024). "This is the first comprehensive pan-cancer analysis of HOXA9 to reveal its crucial role in human cancers." (PMID 38904676, 2024). "Cluster 1 genes enrichment was for just one GO term, transcription regulator complex, and included genes for the cancer-associated transcription factors RUNX1, HOXA9, and MYB." (PMID 38165902, 2024). "Having elucidated the dynamics of cancer pathways, we identified drugs that target aberrantly expressed HOXA9." (PMID 38904676, 2024). "Our data reflect the minimal variation in genetic factors at the HOXA9 locus; specifically, SNVs account for 32% of all cancers." (PMID 38904676, 2024). "We developed a multiplex ddPCR assay targeting ctDNA with a methylation signature specific for breast tissue (LMX1B and ZNF296) and one general marker of cancer (HOXA9)." (PMID 37225860, 2023).
cancer (continued). "A total of 19 midterm and 9 preoperative samples displayed positivity for the cancer specific marker HOXA9 alone." (PMID 37225860, 2023). "Compared to the sensitivity of the cancer specific marker (HOXA9) alone, the addition of two breast tissue specific markers increased the sensitivity of the assay significantly and more than doubled the number of ctDNA positive samples." (PMID 37225860, 2023). "We developed a multiplex ctDNA ddPCR assay including two breast tissue specific (LMX1B and ZNF296) and one cancer specific target (HOXA9)." (PMID 37225860, 2023). "Regulator of Hoxa9, a gene involved in cancer persistence with respect to Setbp1‐mediated myeloid progenitor self‐renewal." (PMID 37872881, 2023). "Understanding the interaction and function role of HOXA9 and its binding partners is benefit for developing potential drug targets in cancer therapy." (PMID 36376832, 2022). "Our analysis herein identified six additional functionally associated HOXA9 proteins, (including HOXA10) which are predicted to interact with HOXA9 and are classified as having a role in transcriptional regulation in cancer." (PMID 35743243, 2022). "Our results with ATRA are consistent with previous studies showing that a decrease of HOXA9 expression in cancer cells occurs upon exposure to ATRA." (PMID 35743243, 2022). "We, thus, interrogated gene expression data of pre-leukemic (overexpressing Hoxa9) and leukemogenic (overexpressing Hoxa9 and Meis1; H9M) murine cell lines to identify cancer vulnerabilities." (PMID 34502319, 2021). "The role of these factors in other cancers is consistent with our findings, which further confirmed the potential suitability of HOXA9 and CRH status as predictors of clinical outcome." (PMID 34623790, 2021). "The aberrant methylation of other genes, such as FHIT, HOXA9, NNK, and MSH3 have also been found to be associated with cancer progression." (PMID 34456184, 2021). "Simultaneous methylation of SOX1 + HOXA9 exhibited a sensitivity of 66.67% with a specificity of 96.0% (AUC = 0.85) for cancer detection in serum cell-free DNA." (PMID 34778370, 2021). "In the context of PDAC, the HOTTIP lncRNA seemed to regulate HOX genes (HOXA9 and HOXA10), and the HOXA9 gene has been shown to promote cancer stem cell proliferation through the Wnt/β-catenin signaling pathway." (PMID 34650983, 2021). "Previous studies have also advocated that the organization of chromatin domains at the HOXA gene cluster contributes to high HOXA9 expression in cancer cells." (PMID 33001025, 2020). "PRMT1 has been identified as a key common downstream mediator for β-catenin/Hoxa9 functions in MLL in the context of cancer stem cells." (PMID 32517078, 2020). "Among the candidate target genes, HOXA9, a member of the HOX gene family, encodes a series of transcription factors with critical roles in cancer." (PMID 31906958, 2020). "The overexpression of HOXA9 is associated with poor outcomes in EOC patients and Hoxa9 regulates the activation of cancer-associated fibroblasts by TGF-β2 in EOC cells." (PMID 33402862, 2020). "In summary, we revealed that candidate transcription factors identified from the CRISPR/Cas9 screen including USF2 and USF1, regulate HOXA9 thereby providing a more comprehensive understanding about how the HOXA9 locus is regulated in human cancer cells." (PMID 33001025, 2020). "An example of HOX gene alteration in cancer, relates with the increased expression of HOXA9 in the most aggressive acute leukaemia and its potential as predictive of poor prognosis." (PMID 33375038, 2020). "Enrichment of CSCs in NSCLC microenvironment contributed to drug resistance and cancer recurrence, and the existed information hinted that circRNA CDR1as/miR-641/HOXA9 pathway regulated cell stemness." (PMID 32655321, 2020). "The first link between NUP98 and cancer came from its identification as a fusion partner with HOXA9 in AML patients." (PMID 30935371, 2019).
cancer (continued). "For the lymphoid-derived cancer cell lines next to the specific surface markers (e.g., CD72, LAIR) associated with T/B-cells, we identified FLT3, HOXA9, MYC, and HEXIM1 as top genes driving the difference between the samples." (PMID 31253180, 2019). "Although HIF-1α acts as a key factor regulating hypoxia response and glucose metabolism in cancer biology, the relationship between HOXA9 and HIF-1α-mediated hypoxia response and metabolic regulation has rarely been explored, especially in cSCC." (PMID 29662084, 2018). "We found that SPARCL1, ENG, TAL1, ATP8A2 and HOXA9 were down-regulated in 99, 94, 89, 65 and 49% of the 82 cancer samples." (PMID 28178989, 2017). "The methylation of the HOXA9 and HOXA10 promoters is associated with cancer progression in various cancers." (PMID 28748001, 2017). "Transcriptomic analyses identified novel HOXA9-target genes with key roles in cancer-related processes, including cell proliferation, DNA repair, and stem cell maintenance." (PMID 25762636, 2015). "Our findings provide new insights regarding strategies to target HOXA9 overexpression in this incurable cancer." (PMID 25762636, 2015). "Previous studies identified hypermethyled promoter regions in some commonly methylated genes (RASSF1A, p16, MLH1, MGMT, HOXA9) in different types of cancers." (PMID 22140553, 2011). "The results showed that some HOX genes in pan-cancer had significant strong correlation (R≥0.8): HOXA9 with HOXA10, HOXB5 with HOXB6 and HOXB8, HOXB8 with HOXB6 and HOXB9, HOXB3 with HOXB4 and HOXB5 and HOXB6, HOXC8 with HOXC9, HOXC9 with HOXC10, HOXD10 with HOXD11." (PMID 39980564, 2025). "In conclusion, we found that the aberrant promotor methylation of OncoMe (SHOX2, RASSF1A, SEPTIN9 and HOXA9) was a cancer-specific alteration and might be a valuable marker to aid in the differentiation of MA." (PMID 41477641, 2025). "Similarly, we observed an association of HOXA9 with PBX1, PBX2, PBX3, and MEIS1 in all 10 cancer types except for STAD." (PMID 38904676, 2024). "Therefore, HOXA9 played different regulation functions for proliferation between normal somatic cells and cancer cells." (PMID 38605318, 2024). "Moreover, our investigation revealed the impact of HOXA9 on various signaling pathways and cancer hallmarks." (PMID 38904676, 2024). "Among the 33 TCGA cancer types analyzed using the RNA-Seq dataset, HOXA9 was found to be highly upregulated in 9 cancer types and downregulated in 2 of the cancer types compared to normal tissues, indicating that HOXA9 acts as an oncogene in the majority of cancer types." (PMID 38904676, 2024). "Notably, the pathways represented by these targets were reported to be significantly involved in acquiring cancer hallmarks, indicating the ability of HOXA9 to regulate downstream pathways to promote cancer progression." (PMID 38904676, 2024). "Based on previous reports that suggested the role of HOXA9 in human cancers, we systematically performed a pan-cancer analysis to determine the differential expression of HOXA9, its mode of regulation, its molecular mechanisms, and its functional implications using valid computational databases." (PMID 38904676, 2024). "We conducted a comprehensive analysis to determine the role of HOXA9 across cancers." (PMID 38904676, 2024). "Assessing the expression of HOXA9 in the different clinical stages might aid in preventing cancer progression." (PMID 38904676, 2024). "The assessment of the correlation of HOXA9 expression with approved antineoplastic drugs revealed that targeting HOXA9 could be the most reliable strategy for preventing cancer progression." (PMID 38904676, 2024). "According to the GDSC, HOXA9 showed a positive correlation with drugs, namely SB52334, dabrafenib, PLX4720, YM155, and UNC0638, indicating that HOXA9 could induce drug resistance in cancer." (PMID 38904676, 2024).